TNF (tumor necrosis factor)
Diseases named in the same sentence as TNF in open-access papers (continued):
Sharing a sentence is not in itself a finding about the gene and the disease.
tumor (continued). "Additionally, M1 TAMs can phagocytize tumor cells through direct physical interactions, while N1 TANs can indirectly regulate phagocytosis of tumor cells through the secretion of the proinflammatory cytokines TNF-α and IL-12." (PMID 34830776, 2021). "Similarly, pDCs purified from tumor samples of ovarian cancer patients also secrete lower amounts of IFNα compared to blood pDCs upon Flu and CpG-A stimulation due to the presence of TGFβ and TNFα." (PMID 33919546, 2021). "However, the interaction between TGF-β and TNF-α during tumor formation is still unclear." (PMID 35069596, 2021). "Moreover, TNF-α derived from TAMs could stimulate tumour cells to release IL-6, contributing to STAT3 activation in TAMs." (PMID 33654093, 2021). "Pro-inflammatory cytokines like TGF-β (transforming growth factor beta), TNF-α (tumour necrosis factor alpha), interkeukins (IL) like IL-1β, and IL-6 (Interleukin) elevate the expression of selectins on the vascular cells, which synchronize with the IL-8 secreted by the tumor cells." (PMID 34837924, 2021). "Thus, our findings indicate that inhibition of CD95 signaling altered the chemotherapeutic effects of gemcitabine, not only by suppressing the pro-inflammatory responses that arose from the CD95L-positive tumor cells but also from the TNF-α and TRAIL signaling in a bi-lateral crosstalk manner." (PMID 34771621, 2021). "TNF-α plays a dual role i.e., it may exhibit pro, as well as anti-tumor activity." (PMID 34837924, 2021). "GSEA showed several tumor hallmarks were enriched in the high-risk group, such as interferon γ response, HEME metabolism, allograft rejection, interferon α response, complement, myogenesis, inflammatory response, KRAS signaling up, TNFα signaling via NF-κB and so on." (PMID 34869365, 2021). "But when we infused ex vivo activated TNFα-/- NK cells after allogeneic HSCT with IC, we observed improved tumor control compared to ex vivo activated TNFα+/+ NK cells, suggesting TNFα may be contributing to CRS in a manner that attenuates the GVT potential of the infused NK cells." (PMID 34489927, 2021). "Furthermore, the engineering of OVs allows enforced expression of genes with therapeutic potential, including TAAs, costimulatory molecules, and cytokines (e.g. GM-CSF, Il-2, IL-12, or TNFα), which can further amplify immune responses and counteract tumor-induced immunosuppression." (PMID 34367185, 2021). "Moreover, TNF-α produced by macrophages has been reported to stimulate the proliferation of fibroblasts in the process of wound healing and acts similarly in tumor tissue to create a fibroblast-rich tumor microenvironment." (PMID 34135469, 2021). "As a result, HDIs may exert their anti-cancer action, at least in part, by decreasing tumour cell responsiveness to TNF-mediated activation of the NF-κB pathway, as TNF-receptor-1 expression and TNF-mediated NF-κB nuclear translocation were all reduced in HDI-treated NSCLC cells." (PMID 34769131, 2021). "However, TNF-α treatment induced neutrophils to kill tumor cells by generating ROS." (PMID 32422991, 2020). "TNF-α may promote or inhibit the progression of tumor depending on its concentration 30,31." (PMID 32201528, 2020). "Therefore, MCL1 amplification, the TMN, and TNF-α, combined with clinical parameters including age, stage, maximum tumor dimension, brachytherapy schemes, and pretreatment hemoglobulin, were selected for the multivariate Cox regression model for survival analyses." (PMID 32527042, 2020). "In addition, the downregulation of the proinflammatory cytokines TNFα and IL-6 in tumor tissue in rats receiving SRD supplemented with falcarinol and falcarindiol is further evidence for the anti-inflammatory action and chemopreventive effects of these dietary polyacetylenes." (PMID 32486470, 2020).
tumor (continued). "By using an ex vivo ovarian cancer (OVCA) model derived from patient samples, enhanced levels of proinflammatory signals (IFNγ, CXCL10, TNFα and IL-2) associated with a concomitant activation of CD4 and CD8 TILs could be observed when tumor cells were infected with TILT-123." (PMID 33202717, 2020). "In addition, we also observed that mice that received combination treatment demonstrated significantly higher levels of IFN-γ, TNF-α, and IL-2 in tumor supernatant and blood when compared to control or single treatment groups, confirming that LB-100 increased cytokine secretion." (PMID 31935881, 2020). "In this system, we demonstrated that cell-to-cell contacts between the tumor cells and the stromal cells, as well as soluble mediators, have led to increased production of inflammatory chemokines; this process was further promoted by stimulation of tumor-stroma co-cultures with TNFα and IL-1β." (PMID 32582148, 2020). "Mice with a deficiency of either tumor necrosis factor (TNF)-α, a master proinflammatory cytokine, or C-C motif chemokine ligand 2 (CCL2), a proinflammatory chemokine, were refractory to the development of malignant tumors in the classical two-stage skin carcinogenesis model." (PMID 33322099, 2020). "For functional enrichment, our results demonstrated that CXCRs and their similar genes may be involved in the immune process, angiogenesis, and tumor initiation and progression via a variety of signaling pathways (e.g., TNF pathway, pathways in cancer) and biological processes (e.g., angiogenesis)." (PMID 33324682, 2020). "In addition, macrophages could contribute to the elimination of nascent tumor cells through the release of nitric oxide (NO) and TNFα, which can be induced through NK2GD triggering." (PMID 32397392, 2020). "Moreover, DGKα is involved in inflammation in tumor cells by positively regulating tumor necrosis factor α (TNFα)-induced nuclear factor kappa-light-chain-enhancer of activated B cells (NF-κB) activation via a PKCζ-mediated Ser311 phosphorylation of the NF-κB subunit p65/RelA." (PMID 32722576, 2020). "In contrast to the experimental models, the effects of TNF-α blockade in cancer cachexia, while complicated by the diversity of disease etiologies, and limitations due to the actions of the corresponding treatments on tumor immunity, have proven less promising." (PMID 33329046, 2020). "Continuous TNF-α stimulation promotes tumor angiogenesis, DNA damage, tumor epithelial-mesenchymal transition (EMT), and other mechanisms to promote tumor survival and metastasis, and its mechanism may be related to the activation of the nuclear factor kappa-B (NF-κB) signaling pathway." (PMID 32149121, 2020). "Moreover, TREM-1 could impact various cytokines, such as IL-8, MCP-1, and TNF-α, in the tumor microenvironment." (PMID 33204302, 2020). "Several cytokines, which can arise from either tumor cells or immunocytes, such as tumor necrosis factor (TNF)-α, interleukin (IL)-1β, IL-6, IL-8, IL-10, and vascular endothelial growth factor (VEGF), have been linked with cancers and can either promote or inhibit tumor development." (PMID 32847533, 2020). "Besides TNF, tumor homing peptides could facilitatedistributionof other cytokines into tumor cells and enhance their therapeuticeffect." (PMID 32023055, 2020). "Last but not least, TNF-α in the TME may also have a downside as it can bind to TNFR2, which is expressed by regulatory Treg cells and MDSCs to protect them from TNF-α induced death, while in the same way reducing the capacity of M1 macrophages to clear tumor cells." (PMID 32290124, 2020). "In addition, the upregulation of the TNF receptor 2 (TNFR2) on tumor cells may foster tumor cell growth over TNFR1-induced killing after the binding of TNF-α." (PMID 32290124, 2020).
tumor (continued). "Indeed, emerging literature suggests that tumour cells may be senstitised to NK cell-mediated and TNF-dependent killing through administration of a SM, and potentially overcome resistance to T cell-directed immunotherapies." (PMID 31947615, 2020). "It should be noted, however, that there is also evidence that IL-6 and TNF-a may be antitumorigenic at higher concentrations, suggesting that the local concentration of these cytokines in the tumor microenvironment is a key factor in tumor progression." (PMID 32973746, 2020). "This could explain TNF-α’s role, acting in a manner contrary to tumor development." (PMID 31936364, 2020). "Finally, mice orally administered with holo-bLf-Dox conjugates showed better survival rates, a marked reduction in tumor growth and Dox-mediated general toxicity, neurotoxicity and cardiotoxicity, as well as an increase in serum levels of TNF-α, IFN-γ, CCL4, and CCL17." (PMID 32183434, 2020). "It is estimated that the hypoxic tumor environment stimulates the production of Hypoxia Inducible Factor-1 (HIF-1) triggering a cascade of pro- angiogenic cytokines such as Tumor Necrosis Factor alpha (TNFα), Vascular Endothelial Growth Factor (VEGF) and Interleukin-8 (IL-8)." (PMID 32613208, 2020). "Although TNF-α can be found at BC tissue level, to date it is unknown whether the TNF-α surrounding the tumor is produced and released by cancer cells as an evasion strategy from the host immune response or whether it is secreted by cells of the immune system that infiltrate the tumor tissue." (PMID 32013102, 2020). "Therefore, GRK2 siRNA was used to examine the molecular interactions of TNF-α in tumor growth, and the obtained results suggested that TNF-α could serve as a new potential therapeutic target in HCC." (PMID 32722054, 2020). "However, tumor‐activated vessels are not the only ones highly susceptible to the destructive TNF effects, also vessels exposed to bacterial products react strongly to TNF with systemic or local Schwarzman reactions." (PMID 31916677, 2020). "DAMPs and cytokines (such as tumor necrosis factor (TNF)-α, interleukin (IL)-6 and IL-1β) released from PDT treated cells may cause acute inflammation and enhance infiltration of innate and adaptive immune cells at the irradiated tumor site." (PMID 37425217, 2020). "While several inflammatory mediators (IL-6, TNF-α, TWEAK, TRAF6, INF-γ, and LIF) have been implicated as drivers of cancer-associated wasting, very little is known about their origin, whether skeletal muscle, immune cell, or tumor-derived." (PMID 32982782, 2020). "Whether this anti-TNF treatment affects the anti-tumor immune response was relatively unknown." (PMID 32486375, 2020). "Moreover, TNF alpha promotes tumor-induced immunosuppression via induction of aberrant CCR4 expression and may represent a new target for immune treatment of GC in the future." (PMID 33182840, 2020). "Anticancer effects of these compounds and their combination with cisplatin were assessed in this tumor mouse model with bioluminescent signaling and histopathology, and a cytokine assay was used to examine expression of inflammatory cytokines IL-1β, IL-6, IL-10, and TNF-α from plasma samples." (PMID 32174830, 2020). "In addition, the systemic elevation of some cytokines, such as TNFα, IL-6, IL-8, and IL-10, observed in GD patients, which are known to promote tumor development, could be involved in the increased tumor growth we observed." (PMID 32085512, 2020). "Notably, tumor-infiltrating NK cells are the main producers of IFN-γ which is important in limiting tumor growth, while the high production of TNF-α by intILC1s and ILC1s can be responsible for the pro-tumorigenic and pro-angiogenic effects of these innate lymphocytes." (PMID 31948072, 2020). "Furthermore, TNF-α secreted by TAM leads to the activation of NF-kB in tumor cells." (PMID 33224886, 2020).
tumor (continued). "In supernatants derived from RANK+/+ tumor acini, many cytokines were upregulated including stromal cell-derived factor-1α, macrophage inflammatory protein-1α, interleukin (IL)-1α, stem cell factor, tumor necrosis factor-α, IL-13, macrophage colony-stimulating factor, IL-10, IL-4, IL-17, and IL-1β." (PMID 33303745, 2020). "Importantly, the enrichment of interferon-gamma (IFN-γ) and tumor necrosis factor (TNF)-related apoptosis-inducing ligand (TRAIL) pathways may reflect the host immune responses towards the presence of the tumor." (PMID 32575471, 2020). "In some tumors a great concentration of tumor necrosis factor α (TNF α) protein was found and transcriptomic analysis has demonstrated that apigenin is able to downregulate half of the genes that normally are upregulated by TNFα, all related to tumor promotion, invasion, and metastatic growth." (PMID 32110931, 2020). "In addition, emodin sensitizes resistant tumor cells to chemotherapeutic agents such as tumor necrosis factor (TNF)-related apoptosis-inducing ligands, as oxaliplatin, gemcitabine, adriamycin, cisplatin, capecitabine, paclitaxel, abiplastin, doxorubicin, and 5-fluorouracil." (PMID 32106621, 2020). "Interestingly, TNF-α regulates the immune system via IL-17 to promote tumor proliferation." (PMID 33664764, 2020). "Therefore, we investigated whether HSD affected Th17 cell differentiation and the related cytokine expression, and found that HSD enhanced the number of Th17 cells and induced TNF-α expression in tumour tissues." (PMID 32265505, 2020). "Similarly, unsensitivity to interferons (IFNs) or lack of perforin, interleukin (IL)-12, tumor necrosis factor (TNF)-α or IL-1β are associated with increased tumor susceptibility." (PMID 32265933, 2020). "Furthermore, H2O2 released by macrophages and neutrophils induces the expression of Tnfa and Tnfr1 in epithelial cells, that in turn release TNFα leading to the upregulation of other proinflammatory and angiogenic factors, hence, sustaining tumor progression in a paracrine loop." (PMID 32733461, 2020). "In a nutshell, M1-like macrophages could produce proinflammatory cytokines like TNF-α and iNOS, and the newly recruited monocytes might also be triggered to modulate to an M1-like phenotype by iron stored in tumor area, forming the cycle for further enhancement of their antitumor effect." (PMID 32548111, 2020). "Moreover, several inflammatory cytokines were found to be significantly upregulated in cancer survivors, while pathway enrichment analyses showed that these were associated with activation of tumor-promoting pathways such as those mediated by MAPK, PI3K-AKT, Ras, and TNF." (PMID 32587352, 2020). "Furthermore, Vδ2Vγ9 T cells possess the characteristics of self-activation and release the Th1-type cytokine interferon gamma (IFN-γ) and other cytotoxic cytokines, such as tumor necrosis factor (TNF), perforin, and granzymes (granzyme A and B), to eliminate tumor cells." (PMID 32849498, 2020). "Despite impairments of productions of TNFα and IFNα, respectively, by circulating cDC2s and pDCs, production of IL‐12p40/p70 by circulating cDC2s together with TNFα and/or IFNλ1 respectively by circulating or tumor‐infiltrating cDC1s and pDCs remained similar to HD." (PMID 33282290, 2020). "Furthermore, monocytes and macrophages in IgE-treated rat tumours showed enhanced intracellular TNFα and IL-10 expression, and significantly upregulated TNFα, MCP-1 and IL-10 levels in the bronchoalveolar lavage (BAL) fluid, compared with IgG- or PBS control-treated groups." (PMID 33203088, 2020). "Another important player in the inflammatory team is TNF-alpha that also plays a dual role in carcinogenesis, while being both a procarcinogen and an anticarcinogen; it has been discovered by a number of researchers both in blood serum and its expression in the tumor." (PMID 32963755, 2020).
tumor (continued). "Moreover, we found that endothelial TNF‐R1 reactivation knockout mice were completely resistant to acute TNF toxicity, indicating that directing TNF activity only to endothelial cells of the tumor vasculature could generate an effective yet safe therapy." (PMID 31912630, 2020). "The skin inflammatory process promotes skin dryness, induces infiltration of inflammatory cells, increases skin thickening and stimulates the membrane receptors of keratinocytes which promotes the release of various inflammatory mediators such as TNFα, IL-8, IL-1α, IL-6 and IL-12." (PMID 33371334, 2020). "The novel TNF could also improve adoptive T‐cell therapy using T cells engineered with chimeric antigen receptors by increasing the number of T cells infiltrating the tumor." (PMID 31916677, 2020). "paragordonae alone, or in synergism with cisplatin in tumor-bearing mice, improved mice survival rate and enhanced a strong activation of the immune system through natural killer (NK) and DCs activation, and release of cytokines such as IL-12 or tumor necrosis factor (TNF-α)." (PMID 32635668, 2020). "Moreover, synthesis of tumor necrosis factor-α (TNFα) by liver Kupffer cells and activation of nuclear factor κB (NFκB), which may promote tumor expansion, are blocked by glycine." (PMID 32878230, 2020). "However, IL-6 can act also as anti-inflammatory agent interacting with TNFα and could potentially favor tumor progression." (PMID 32033013, 2020). "Thus, it is reasonable to hypothesize that DCs infiltrating the tumor microenvironment (TME) could be stimulated to secrete TNF-α and IL-6, and are more likely to do so if they were to come in contact with EC (or tumor cells) expressing Gal-3." (PMID 33154744, 2020). "The current research identified that infiltrated dendritic cells in the tumor microenvironment could synthesize hormones and secret the paracrine factors such as TNF, WNT10A, PDGFA, and NRG1 which could sensitize sensory neurons to promote neuropathic pain associated with multiple cancers." (PMID 32434423, 2020). "Collectively, this study suggested IL10 could inhibit the growth of the transplanted tumor in vivo and prolong survival of mice, and the primary mechanism may be the indirect inhibition of pro-inflammatory cytokines IL6 and TNF-α secretion and tumor angiogenesis formation." (PMID 32742480, 2020). "However, TNFα in the tumor microenvironment was on the level of ng35." (PMID 33214550, 2020). "Thus, data obtained suggests that TNFα/TNF-R1-dependent mechanism plays an important role in DC-mediated cytotoxicity against autologous tumor cells and that defective TNFα-mediated DC cytotoxicity is responsible for reduced effector functions of patient IFN-DCs." (PMID 32326230, 2020). "In line with this, two recent reports have shown that blocking TNF in tumor-bearing mice enhances to some extent the antitumor effect of immunotherapy with anti-PD1 mAb or an anti-PD1 + anti-CTLA-4 combinations of mAbs, while at the same time TNF-blockade prevents associated immunopathology 24,25." (PMID 32292509, 2020). "The treatment increased the expression of IFNγ and CXCL9/CXCL10 in the tumor, as well as increased serum IFNγ/TNFα and expression of tumor-infiltrating lymphocytes, which may indicate the effectiveness of durvalumab/olaparib combination therapy in inducing an immune response in the tumor." (PMID 33327450, 2020). "This may relate to the paradoxical tumour-suppressive effects of TNF, such as cytotoxicity." (PMID 32805626, 2020). "A possible explanation for this could be the lack of association of MIF and TNFα which play a role in the site of tumor where the inflammatory process is exacerbated; therefore, more studies are necessary for the determination of these cytokines in situ." (PMID 31978276, 2020). "TNF-mediated bystander killing maybe underlie the effects of T cells on antigen-negative tumor cells." (PMID 33344447, 2020).